EZH2 (enhancer of zeste 2 polycomb repressive complex 2 subunit)
Diseases named in the same sentence as EZH2 in open-access papers (continued):
Sharing a sentence is not in itself a finding about the gene and the disease.
cancer (continued). "It is possible that inhibition of EZH2 might affect the fate of cancer stem cells, although we were unable to demonstrate the evidence for the existence of stem cells in our experiments." (PMID 18980680, 2008). "Recent studies have shown that EZH2 is highly expressed in several advanced cancers." (PMID 15856046, 2005). "Although EZH2 target genes have not been directly linked to cancer development, evidence for EZH2 function in at least B-cell development is beginning to emerge." (PMID 14970850, 2004). "Moreover, the effect of EZH2-K348cr on cancer cell migration was evaluated." (PMID 41544165, 2026). "Therefore, EZH2 inhibitors may offer a valuable therapeutic approach for both addressing morphine tolerance and combating various cancers." (PMID 41111460, 2026). "Importantly, the combination of entinostat and tazemetostat produced superior therapeutic effects, suggesting that dual targeting EZH2 and HDACs may provide a promising treatment option for this aggressive cancer." (PMID 40464712, 2025). "The association between EZH2 and circadian genes, including CLOCK and BMAL1, could shed light on the molecular mechanisms that drive HCC progression and underscore the significance of circadian regulation in cancer biology." (PMID 41298718, 2025). "By silencing or activating target proteins, EZH2 is involved in many links of cancer tumorigenesis and development, such as cell proliferation, epithelial–mesenchymal transition, invasion, and drug resistance of cancer cells, making it an important biomarker for cancer therapy." (PMID 40028035, 2025). "Therefore, exploring the combination of an EZH2 inhibitor with cisplatin, or administering the EZH2 inhibitor as a secondary treatment following cancer recurrence post-cisplatin therapy, may represent a promising therapeutic strategy." (PMID 41614754, 2025). "Indeed, EZH2 is found to be overexpressed in various cancers with poor neoantigen presentation." (PMID 41252204, 2025). "We also analyzed the expression of genes involved in epigenetic factors, such as EZH2 (Enhancer of zest homolog 2), involved in histone modifications, and HOTAIR (a long non-coding RNA), two genes that have been associated with tumorigenesis in several cancers." (PMID 40868070, 2025). "Collectively, these findings indicate that EZH2 inhibition enhances immune responses through epigenetic reprogramming in the genome of LS mice, establishing a promising framework for the clinical development of EZH2 inhibitors as a cancer prevention strategy for LS carriers." (PMID 39946195, 2025). "An emerging number of studies suggest that epigenetic reprogramming of EMT via EZH2 inhibitors could promote anticancer effects, as EMT induction poses a significant challenge in the management of HPV-associated cancers, severely impacting efforts to extend patient survival." (PMID 41614754, 2025). "Moreover, AP-2 family members regulate metabolic processes through their downstream targets, with TFAP2A shown to increase EZH2 expression by perturbing the activity of the nucleosome remodeling complex, contributing to the metabolic rewiring characteristic of cancer cells." (PMID 41373739, 2025).
cancer (continued). "Given the potential synthetic lethality relationship between ARID1A and EZH2 in cancer cells, the current evidence suggests that EZH2 could be a new target for synthetic lethality that can be targeted with drugs in cancers with ARID1A deficiency, as confirmed in this study." (PMID 39773749, 2025). "YAP recruits enhancer of zeste homolog 2 (EZH2), the catalytic subunit of polycomb repressive complex 2 implicated in H3K27 methylation, leading to the silencing of Jumonji domain-containing protein D3, a trimethyl demethylase for H3K27me3 in carcinoma cell lines." (PMID 40827349, 2025). "However, it is unknown if and how cell–cell interactions and extracellular matrix (ECM) in the TME influences EZH2’s function in cancer cells." (PMID 37992808, 2024). "In addition to activating mTORC1, SLC7A5 can also facilitate MYC and EZH2 signaling in cancer cells, while SLC3A2 has also been confirmed to facilitate uncontrolled proliferation of cancer cell through AKT, MAPK, and cell cycle-related P21/P27 signaling pathways." (PMID 38267663, 2024). "Thus, EZH2 inhibitors (EZH2is) have been pursued as cancer treatments." (PMID 38911968, 2024). "With ongoing clinical trials and preclinical studies supporting the efficacy of both EZH2 inhibitors and combination therapies, the landscape of treatment for CNS tumors is poised for transformative change, offering new hope for patients facing these challenging cancers." (PMID 39456545, 2024). "Given the emerging evidence that EZH2 influences various metabolic pathways in cancer, this connection between glutamine metabolism, ferroptosis regulation, and the role of EZH2 could represent an additional mechanism by which EZH2 promotes tumorigenesis and resistance to ferroptosis." (PMID 39518098, 2024). "This collective evidence strongly indicates that EZH2 not only exerts its influence on PD‐L1 expression at the transcriptional level but also significantly impacts PD‐L1 protein stability, underscoring its multifaceted regulatory role in the modulation of PD‐L1 in cancer cells." (PMID 38520088, 2024). "Therefore, developing alternative therapeutic strategies that relieve hypoxic TME may be an effective way to improve the outcome of EZH2 inhibition in cancer treatment." (PMID 38911968, 2024). "Moreover, EZH2 has been reported as a multifaced regulator across different types of cancers, potentially functioning both as an oncogene and a tumor-suppressor gene in cancer." (PMID 39703843, 2024). "Furthermore, a correlation between EZH2 expression and the response to immunotherapy has been identified in various types of cancer, indicating that combining EZH2 inhibitors with immunotherapy may enhance treatment efficacy." (PMID 39103941, 2024). "These modifications also change the functions of EHMT1 and EZH2 from transcription corepressors to possible coactivators, highlighting the significant role of posttranslational modifications of histone-modifying proteins in mediating epigenetic reprogramming in cancer." (PMID 37663929, 2023). "Moreover, the dependency of many cancers on EZH2 highlights broader therapeutic applications." (PMID 36635503, 2023). "So EZH2 is often up regulated in primary tumor cancers, which may help cancer cells proliferate." (PMID 36809239, 2023). "Similarly, EZH2 knockdown also led to a significant decrease in cell growth compared with mock-depleted control cells, and ectopic expression of EZH2 rescued the growth potential of cancer cells." (PMID 37069142, 2023). "However, the evidence thus far suggests that targeting EZH2 may represent a promising approach to enhance the effectiveness of immune-based cancer therapies." (PMID 38077327, 2023). "Thus, the combination of EZH2i with other epigenetic drugs capable of disrupting the transcriptional reprogramming of cancer cells triggered by EZH2-targeted therapy may be a rational strategy to increase EZH2 inhibition effectiveness, also in advanced mCRPC." (PMID 36629431, 2023).
cancer (continued). "Based on these findings, we hypothesized that cancer-promoting mutations (i.e., ARID1A) increase PRC2 complex activity (including expression of the EZH2 component) and induce an HCV/alcohol-mediated stem cell program (slow growing cells), leading to TIC-initiated HCC development." (PMID 37744383, 2023). "Therefore, targeting H3K27Me3 via EZH2 is a promising cancer therapy." (PMID 37627320, 2023). "In liver cancer caused by hepatitis B, HBX competes with EZH2 to bind to DLEU2, forming a complex that binds to the TRIMB/CCNB2 promoter, thereby promoting the replication and transcription of covalently closed circular DNA (cccDNA) and promoting cancer progression." (PMID 37095423, 2023). "This implies that EZH2–REST axis may be involved in maintaining neural stemness in cancer cells." (PMID 37537688, 2023). "While all these data support phosphorylation-induced dysregulation of EZH2 activities in certain cancer contexts, further investigation in this aspect is still needed and exactly how EZH2 phosphorylation modulates its function in the process of tumorigenesis remains unclear." (PMID 37069142, 2023). "Because SHR2554 is a novel, highly effective, and selective oral EZH2 inhibitor that may be frequently used in malignant tumors in the future, we hope that the results here will help researchers design and conduct future phase II/III studies and be good for clinical use and promotion of SHR2554." (PMID 35841331, 2023). "Extrapolating from findings in other cell types, several non-mutually exclusive mechanisms could be at play, including direct modification or transcriptional regulation via histone methylation of cell cycle regulators, stimulating EZH2 activity, or regulating Myc activity, as found in cancer cells." (PMID 37310381, 2023). "Importantly, several studies suggest that EZH2 is a critical driver of immune response modulation by cancer cells, mediating immune evasion by downregulation of genes involved in immune activation, upregulation of immune checkpoints, and generation of an immunosuppressive TME." (PMID 36647827, 2023). "Furthermore, it was already demonstrated in several cancer entities that EZH2 might be involved in cisplatin resistance." (PMID 36900361, 2023). "In addition, some EZH2 inhibitors have been proven efficient in some poor prognosis cancers." (PMID 37147437, 2023). "In addition, inhibition of EZH2 by Tazestat or GSK126 can lead to the synthetic lethality of SMARCA4, SMARCB1, PBRM1, and other SWI/SNF chromatin remodeling complex subunit-deficient cancers." (PMID 38008753, 2023). "In addition, miR‐124 manifests the same action on EZH2 in cancer cell lines." (PMID 35087589, 2022). "In addition, EZH2 loss significantly promoted the development of myelodysplastic syndrome induced by transcription factor Runx1 mutation, and loss of SUZ12 synergizes with neurofibromin 1 (NF1) mutations to amplify Ras signaling to drive cancer." (PMID 36076977, 2022). "Additionally, our results indicate that ERβ can function as a molecular switch for EZH2 and repurpose it for anti-cancer effects, findings that may help clarify the paradox between EZH2, H3K27me3, and TNBC patient outcomes." (PMID 35177654, 2022). "Interestingly, EZH2, BMI1 and the histone demethylase (HDM) Lysine Demethylase 6B (KDM6B also called JMJD3), which can remove H3K27me3, have been associated with EMT, poor prognosis and metastasis in cancer." (PMID 36135315, 2022). "Notably, it has been proposed that abnormally high levels of EZH2 found in cancer cells may shift expression profiles toward a stem-cell-like state." (PMID 35163453, 2022). "Therefore, it was suggested that targeting EZH2 could potentially overcome the resistance to immunotherapy in several cancer types." (PMID 36230683, 2022). "Furthermore, miRNAs can regulate therapy response of cancer cells via affecting EZH2 signaling." (PMID 35236381, 2022).
cancer (continued). "Efforts to therapeutically target EZH2 have generally focused on inhibition of its methyltransferase activity, although it remains less clear whether this is the central mechanism whereby EZH2 promotes cancer." (PMID 35013218, 2022). "The role of dual G9a and EZH2 inhibition in other cancers remains unclear." (PMID 35409271, 2022). "Thus, investigating whether MALAT1 can influence cancer progression through its regulation of EZH2 warrants further research." (PMID 36419933, 2022). "Therefore, new strategies for manipulation of EZH2 may be developed to improve cancer therapy in the near future." (PMID 35656182, 2022). "Indeed, several papers regarding the EZH2 SNPs and cancer progression have been published." (PMID 35813302, 2022). "Therefore, EZH2 has been proposed as a target for therapy of these cancers." (PMID 35406676, 2022). "However, resistance to immune checkpoint inhibitors has been observed in various tumors and EZH2 inhibition enhances anti-cancer immunity and prevents checkpoint inhibitor resistance via improving T regulatory cell trafficking and elevated antigen presentation." (PMID 35236381, 2022). "Moreover, EZH2-mediated H3K27me3 has been explored in cancers." (PMID 35414117, 2022). "Moreover, it has been demonstrated that EZH2 overexpression could suppress apoptosis in a variety of cancers, promoting cancer cell survival." (PMID 36430394, 2022). "Also, since changes in miRNA expression appear to be a common feature of cancers, including HCC, inhibition of miRNAs targeting EZH2 may be associated with aberrant overexpression of EZH2." (PMID 36071871, 2022). "Cancer genomic sequencing data also suggest that EZH2 might have a PRC2-independent function." (PMID 36612203, 2022). "Therefore, EZH2 is regarded as a potential new target for cancer treatment." (PMID 36009484, 2022). "Because the reduction of Ikaros and EZH2 impact cancer cell growth and increase recognition of infected cells by the host immune system through increased ICAM-1 and B7-2, Pom may have both a direct and an indirect effect on the survival of HTLV-1-infected cells." (PMID 35602479, 2022). "In addition, genetic mutations in epigenetic factors such as the SWI/SNF complex, frequently observed in various cancer types, cause H3K27me3 accumulation by EZH1 and EZH2, and dual inhibitors might be effective in these cases as well." (PMID 36239901, 2022). "Therefore, screening a larger library of natural and synthetic compounds to identify compounds that target the interaction between HOTAIR and PRC2 complexes could be an alternative strategy for targeting HOTAIR/ EZH2-dependent cancers." (PMID 36100611, 2022). "The upregulation of MINCR may participate in cancer initiation via triggering the EZH2 expression." (PMID 34923811, 2022). "Also, novel EZH2 inhibitors targeting EZH2 post-translational modifications may have therapeutic potentials in cancer therapy." (PMID 35509102, 2022). "Finally, proliferation and metastasis of cancer cells are regulated by lncRNA/EZh2 axis." (PMID 35236381, 2022). "Moreover, EZH2 is also an oncogene in many cancers, including GBM47,48." (PMID 35970825, 2022). "However, H3K27ac co-inhibition improved efficacy of EZH2 inhibitors but also activates MAPK pathway in some cancers, suggesting that inhibition of EZH2 itself may feedback activation of some signaling pathways in a context-dependent manner." (PMID 33794893, 2021). "EZH2 inhibitors have been hypothesized to prevent SCLC transformation in high-risk triple-mutant cancers, based on SCLC data and small cell transformation in other cancers." (PMID 34572868, 2021). "This may be the reason why EZH2 can serve as a target for multiple cancer treatments." (PMID 34112092, 2021). "In addition to its function as a competitively endogenous RNA (ceRNA), sponging miRNA in human cancers, Snhg15 was described to be localized and to act in the nucleus, e.g., by interacting with EZH2 that catalyzes repressive trimethylation at histone 3 (H3K27me3)." (PMID 33572758, 2021).
cancer (continued). "Therefore, inhibition of EZH2 protein could provide new ideas and methods in the treatment of cancers." (PMID 34737956, 2021). "There are 10 highly significant, direct and physical associators with a confidence score of ≥5.0 namely – RELA, HMOX2, EZH2, p-10Y-ERBB3-1, WDR1, ERRFI1, PRG2, FMR1, DEFA6-(?-100), cytf_human and the majority of the network associators of POTEE are epigenetically activated in many cancers." (PMID 34788504, 2021). "A vast number of studies suggested that EZH2 is dramatically elevated in a wide spectrum of human malignancies, such as those of the lung 18, breast 19, prostate 20, gastric 21 and hematological malignancies 22, which provides a promising target for anti-cancer drug therapy." (PMID 33664859, 2021). "Hence, the crucial role of Ezh2 in maintaining the functionality of effector T cells and formation of memory precursor T cells emphasizes the potential detrimental effects of targeting Ezh2 in T cells on the outcome of cancer immunotherapy." (PMID 33403469, 2021). "In addition, a number of other lncRNAs could also work as decoys to antagonize different microRNAs and thus promote EZH2 expression, leading to enhanced cancer progression and resistance to chemo- or radiotherapies." (PMID 34512145, 2021). "Indeed, besides its PRC2-dependent methylation function, EZH2 was also documented in cancer cells to physically interact with various proteins to positively regulate their protein stability as well as to cooperate with several transcription factors to stimulate gene transcription." (PMID 33803922, 2021). "Therefore, we hypothesized that inhibiting the AMPK activity will promote the EZH2 activity and will further enhance the anti-proliferative impact of EZH2 inhibitor in E.C.M. detached cancer cells." (PMID 33531586, 2021). "However, targeting of EZH2 may be unpredictable as it has been shown to have opposing effects across cancer types." (PMID 33197277, 2021). "However, the mechanism of EZH2 overexpression in cancers has remained elusive." (PMID 33849069, 2021). "Nevertheless, the current understanding of EZH2 expression and activity mediated by lncRNAs will not only be exemplificative in the studies of other oncogenic networks regulated by lncRNAs, but also provide insights in discovering novel therapeutic targets of cancer treatments." (PMID 34512145, 2021). "Besides, UHRF1 overexpression is observed in numerous cancers as is the case with EZH2, which may enable us to apply what is learnt from RB's case to other UHRF1‐overexpressing cancers if UHRF1 inhibitors can be successfully developed." (PMID 32840881, 2021). "These two elegant study together suggested the specific immune microenvironment of LM and ICI based combination therapy (e.g. plus CTLA-4 inhibitor, EZH2 inhibitors, radiotherapy, etc.)could rescue systemic antitumor immunity and improve the prognosis of cancer patients with LM." (PMID 34248939, 2021). "Moreover, EZH2 is involved in the regulation of immune cells (e.g., T cells, natural killer cells, dendritic cells, and macrophages), which are essential components in the cancer microenvironment." (PMID 35008250, 2021). "Indeed, numerous studies on EZH2 have highlighted its role in cell survival and proliferation, epithelial to mesenchymal transition and invasion, and immune evasion, underscoring its function as a master regulator of multiple hallmarks of cancer." (PMID 33050946, 2020). "Moreover, there is recent substantial data which suggested that miR-33a could negatively regulate EZH2 in cancer progression by direct interaction in TNBC." (PMID 33014831, 2020). "However, EZH2 overexpression isobserved in many malignant neoplasms." (PMID 33456979, 2020). "EZH2 expression in effector T cells and dendritic cells (DCs) could promote anti-cancer immunity." (PMID 32723346, 2020).